CYC1 (cytochrome c1)
Diseases named in the same sentence as CYC1 in open-access papers:
CYC1 is named in the same sentence as 49 diseases in open-access papers, as found by Europe PMC text mining. Sharing a sentence is not in itself a finding about the gene and the disease. The quoted sentences say what the papers report.
breast carcinoma (9 papers, 2016 to 2024). "On the basis of the results above, upregulation of CYC1 was associated with breast cancer progression and correlated to cancer cell metastasis." (PMID 27239088, 2016). "All of these results indicated that the suppression of CYC1 inhibited breast cancer cell metastasis." (PMID 27239088, 2016). "Then we confirmed that CYC1 contributed to metastasis and proliferation in two highly metastatic human breast cancer cell lines." (PMID 27239088, 2016). "We are the first to find that CYC1 is upregulated in breast intraductal carcinoma, supporting the standpoint which suggests adaptive metabolic reprogramming in breast cancer cells, especially in those which are likely to have metastatic dissemination." (PMID 27239088, 2016). "Our results can indicate that CYC1 can serve as a biomarker suggesting high probability of tumor metastasis and poor prognosis in patients with breast cancer." (PMID 27239088, 2016). "In this study, we found increased expression levels of CYC1 in breast cancer tissues, which was negatively correlated with clinical outcomes." (PMID 27239088, 2016). "We are the first to find that CYC1 is upregulated in breast cancer tissues and CYC1 expression is negatively correlated with breast cancer patient survival." (PMID 27239088, 2016). "And higher expression of CYC1 correlates with poor prognosis in breast cancer patients using online databases and tools." (PMID 27239088, 2016). "The result suggested that breast cancer patients with higher expression levels of CYC1 exhibited lower survival rates (p < 0.01)." (PMID 27239088, 2016). "The data in this report suggests that silencing CYC1 decreases the metastasis and proliferation in breast cancer cells." (PMID 27239088, 2016). "Then we found silencing CYC1 suppressed metastasis and proliferation in two highly metastatic human breast cancer cell lines MDA-MB-231 and MDA-MB-435S cells." (PMID 27239088, 2016). "Cytochrome c-1 (CYC1) is found to play an important role in breast cancer patients." (PMID 33420254, 2021). "In conclusion, the proliferation of breast cancer cells was suppressed by CYC1 knockdown." (PMID 27239088, 2016). "Our results indicated that CYC1 plays crucial roles in breast cancer progression and might be a predictive factor assisting future patient diagnosis." (PMID 27239088, 2016). "But in the future, we may find new ways to overcome the toxic to normal and molecule inhibitors targeting CYC1 will be found to be effective treatment strategies for breast cancer." (PMID 27239088, 2016). "In addition, using online integrated databases, we are the first to find and report that CYC1 expression is negatively correlated with breast cancer patient survival." (PMID 27239088, 2016). "To ascertain whether CYC1 was differentially expressed in malignant breast tumors, we performed and analyzed immunohistochemistry (IHC) on human breast intraductal carcinoma, as well as benign breast tumor tissue." (PMID 27239088, 2016). "Thus, in the future, elevated levels of expression of CYC1 and UQBP could be used to identify high-risk ER(+) and ER(−) breast cancer patients that might benefit from treatment with atovaquone, a complex III inhibitor." (PMID 27136895, 2016). "From the results, we found that mRNA expressions of SLC19A1, CYC1, RRM2B, and OCRL were clearly elevated in breast cancer, while RPS14 expression was considerably decreased." (PMID 35574387, 2022). "And for the survival analyses of OS, high expressions of SLC19A1, CYC1, RRM2B, and OCRL and downregulation of RPS14 were significantly related to more unfavorable OS in breast cancer, which further confirmed the validity of selected genes." (PMID 35574387, 2022). "These subtype-specific breast cancer metabolism signatures contained a common set of five genes (SQLE, PYCRL, TSTA3, CYC1 and SLC39A4) which were co-amplified with MYC on chromosome 8q24 and showed a positive correlation with hypoxia." (PMID 27358048, 2016).
breast carcinoma (continued). "Thus, knockdown of CYC1 sharply decreased the activation of mitochondrial complex III and activated AMPK in human breast cancer cells." (PMID 38561386, 2024). "Cytochrome c1 (CYC1), an important subunit of mitochondrial complex III, was found to be upregulated in breast cancer and might be a predictive factor assisting future patient diagnosis, which was consistent with the results of our study." (PMID 35574387, 2022). "By performing the LASSO Cox regression analysis with 9 candidate genes in breast cancer patients of TCGA-BRCA training dataset, 5 pivotal genes were unearthed to establish the prognostic signature, Lactate Metabolism Index, namely LMI, including RPS14, SLC19A1, CYC1, RRM2B, OCRL." (PMID 35574387, 2022).
osteosarcoma (6 papers, 2009 to 2025). A usually aggressive malignant bone-forming mesenchymal neoplasm, predominantly affecting adolescents and young adults. "Overexpression of cytochrome C1 (CYC-1) was validated as a candidate biomarker for early osteosarcoma diagnosis." (PMID 36077137, 2022). "In another study, it was observed that silencing CYC1 by shRNA transfection also inhibits proliferation in human osteosarcoma (OS) cells." (PMID 33420254, 2021). "The Cyc1 gene plays an important role in the development of nasopharyngeal carcinoma and osteosarcoma [30." (PMID 26869356, 2016). "However, elevated CYC1 with a potential function in resisting apoptosis has been found in uveal melanoma and osteosarcoma." (PMID 40405591, 2025). "However, silencing of CYC1 (using an shRNA approach) in osteosarcoma cell lines effectively inhibits cellular proliferation, sensitizes the cells to apoptotic cell death and inhibits their ability to form tumors in xenograft models." (PMID 27136895, 2016). "The result confirmed that CYC-1 may be a promising biomarker for early diagnosis of osteosarcoma." (PMID 19445706, 2009).
Alzheimer disease (3 papers, 2016 to 2022). A progressive, neurodegenerative disease characterized by loss of function and death of nerve cells in several areas of the brain leading to loss of cognitive function such as memory and language. "While Silberberg and colleagues found TFRC and RPLP0 as the most stable reference genes in schizophrenia and bipolar disorders, Penna and colleagues found CYC1 and EIF4A2 as the best reference genes in Alzheimer’s disease." (PMID 27754318, 2016).
hepatocellular carcinoma (3 papers, 2020 to 2023). A malignant tumor that arises from hepatocytes. "There are examples of UQCRH levels correlating with other CIII subunits, such as UQCRB, UQCRC2 and CYC1 expression in hepatocellular carcinoma." (PMID 34750991, 2021). "Furthermore, their inhibitory effects on Hep-G2 cell proliferation suggest that their corresponding target proteins, CYC1 and SMN1, may be critical for the survival of hepatocellular carcinoma cells." (PMID 37594310, 2023). "Of these five drugs, tafenoquine succinate (a FDA-approved antimalarial drug targeting CYC1) and branaplam (a Phase 3 clinical trial drug targeting SMN1 for the treatment of spinal muscular atrophy) have not been reported as being associated with hepatocellular carcinoma." (PMID 37594310, 2023).
hypoglycaemia (2 papers, 2017 to 2021). "Of the ten nuclear‐encoded structural subunits of CIII, only variants in UQCRC2, UQCRB, UQCRQ and CYC1 have been reported in mitochondrial disease cases associated with hypoglycaemia, lactic acidosis, ketosis and hyperammonaemia." (PMID 34750991, 2021). "These individuals with mutations in UQCRB, UQCRC2, and CYC1 presented with neonatal or early infancy onset, recurrent metabolic crises with elevated lactate and hypoglycaemia, from which they completely and quickly recovered with intravenous glucose." (PMID 28804536, 2017).
oral squamous cell carcinoma (2 papers, 2021 to 2022). "A study showed that overexpression of C5orf66-AS1 can prevent oral squamous cell carcinoma through suppressing cell growth and metastasis by modulating CYC1." (PMID 35909900, 2022).
asthma (1 paper, 2020). "Only 3 (PTCD1, CYC1 and MT-CO1) of the 48 significantly differentially expressed genes were more highly expressed in individuals with asthma; the other 45 had lower expression in individuals with asthma as compared with individuals without asthma." (PMID 33237978, 2020).
breast tumor (1 paper, 2016). "We found that CYC1 was upregulated in breast tumor tissues, especially in tissues with lymph node metastasis." (PMID 27239088, 2016).
colorectal cancer (1 paper, 2023). A primary or metastatic malignant neoplasm that affects the colon or rectum. "CYC1 is a metabolism-related gene that is downregulated in colorectal cancer by several miRNAs after m6A modification, thereby reprogramming the mitochondrial metabolism in colorectal cancer." (PMID 37091868, 2023).
glioblastoma (1 paper, 2019). The most malignant astrocytic tumor (WHO grade IV). "Moreover, to investigate the reliability and the integrity of our NGS transcription data results for each compartment, we evaluated the expression of genes considered as housekeeping candidates in human normal brain tissue, glioblastoma and endothelial cells (RPL13A, RPL4, CYC1, EIF4A2)." (PMID 31231613, 2019).
lactic acidosis (1 paper, 2021). Metabolic acidosis characterized by the accumulation of lactate in the body. "For instance, cytochrome c1 variants were described in two patients with early‐onset episodic acute metabolic ketoacidosis, lactic acidosis, hyperammonaemia and insulin‐responsive hyperglycaemia triggered by infection and febrile illness during childhood." (PMID 34750991, 2021).
malaria (1 paper, 2017). Malaria is a serious and sometimes fatal disease caused by a parasite that commonly infects a certain type of mosquito which feeds on humans. "We demonstrate that P. falciparum Cyc1 (PfCyc1) complements a G1 cyclin-depleted Saccharomyces cerevisiae strain and confirm that other identified malaria parasite cyclins do not complement this strain." (PMID 28611247, 2017).
myocardial infarction (1 paper, 2024). Gross necrosis of the myocardium, as a result of interruption of the blood supply to the area, as in coronary thrombosis. "Ventricular expression of 10 central MitoDEGs (Aco2, Atp5a1, Ndufs3, Ndufv1, Cyc1, Suclg1, Sdha, Sdhb, Cs, and Ndufs2) was verified in a mouse model of myocardial infarction using PCR." (PMID 39775580, 2024).
nonalcoholic steatohepatitis (1 paper, 2020). "Additionally, in the nonalcoholic steatohepatitis (NASH) model, the YWHAZ and ACTB genes were found to be the most stable and the CYC1 and B2M genes were the least stable." (PMID 32089674, 2020).
ovarian carcinoma (1 paper, 2025). A malignant neoplasm originating from the surface ovarian epithelium. "The Kaplan‒Meier plotter database results showed that high expression of TFAM, HSPE1, and CYC1 was associated with an overall poor prognosis in ovarian cancer." (PMID 39927160, 2025). "The protein levels of TFAM, HSPE1, and CYC1 were significantly increased in ovarian cancer tissues compared with normal tissues." (PMID 39927160, 2025). "Furthermore, the protein levels of TFAM, HSPE1, and CYC1 varied according to clinical stages of ovarian cancer." (PMID 39927160, 2025). "The results from the TCGA database showed that HSPE1 and CYC1 were significantly upregulated in ovarian cancer tissues, but TFAM was not statistically significant." (PMID 39927160, 2025). "The protein level of CYC1 in stage I, III, and IV ovarian cancer tissues was not significantly different from that in normal tissues." (PMID 39927160, 2025).
prostate carcinoma (1 paper, 2025). A carcinoma that arises from epithelial cells of the prostate gland. "This metabolic plasticity is increasingly recognized in prostate cancer, though the role of CYC1 specifically in this process has not been explored." (PMID 40405591, 2025).
serous ovarian cancer (1 paper, 2025). "First, analysis of EOC RNA-seq data (GSE209964) from the GEO database showed that the mitochondrial genes TFAM, HSPE1, and CYC1 were significantly upregulated in high-grade serous ovarian cancer." (PMID 39927160, 2025).
cancer (15 papers, 2008 to 2025). A tumor composed of atypical neoplastic, often pleomorphic cells that invade other tissues. "A number of CYC-1 mutations related to tumor or cancer occurrence have been reported." (PMID 19445706, 2009). "We identified dozens of proteins with high protein level variability across the different cancer regions, including CYC1 and ALDH3A1, suggesting spatial differences in metabolic activity and oxidative stress adaptation." (PMID 41418981, 2025). "These cancers also depend on a set of hemoproteins, such as cytochrome c-1 (CYC1), succinate dehydrogenase complex subunit C (SDHC) for cellular respiration, and DGCR8 for microRNA biogenesis, each of which uses heme as a co-factor." (PMID 38649187, 2024). "The gene essentiality analysis also highlighted the importance of heme trafficking (e.g., heme importer FLVCR2) and key hemoproteins (e.g., CYC1) in cancer cell survival." (PMID 38649187, 2024). "CYC1 was significantly upregulated in both cancers treated by PtII56MESS, which was also observed by Western blot analysis in cytochrome c." (PMID 39061185, 2024). "Cytochrome C gene (CYC1) was significantly upregulated in both cancers treated with PtII56MESS treatment." (PMID 39061185, 2024). "Although UQCRH is also involved in electron transport and the maturation of cytochrome c1, its role in cancer progression is controversial." (PMID 34133843, 2022). "Expression of CYC1 was identified to be significantly elevated in malignant tumor tissues, relative to benign tumor tissues." (PMID 27239088, 2016). "As a target for cancer therapy, CYC1 can avoid redundant changes, which may lead to unpredictable results and effectively inhibit metastasis in cancer cells." (PMID 27239088, 2016). "Finally, the role of CYC1 in cancer progression is confirmed using a CYC1 siRNA in vitro transfection system, and our results can indicate that CYC1 can serve as a biomarker suggesting high probability of tumor metastasis and poor prognostic." (PMID 27239088, 2016). "Very little is known about the role of CYC1 in cancer pathogenesis." (PMID 27136895, 2016). "Above all, we draw the conclusion that deficiency of CYC1 was responsible for reduced activity of mitochondrial complex III, increased ratio of AMP to ATP, and then increased phosphorylation of AMPK, which inhibit cancer cells' abilities for invasion and migration." (PMID 27239088, 2016). "Taken together with our current data, these results suggest that atovaquone treatment may be an effective new strategy for targeting the Cytochrome bc1 complex (especially MT-CYB and CYC1) in cancer, to prevent the proliferative expansion of CSCs and tumor growth." (PMID 27136895, 2016). "In the present study, the up-regulated expressions of the Sdhd, Cyc1, and Atp5g3 genes are consistent with metabolic reprogramming, which might switch the Warburg effect to oxidative phosphorylation with slowing energy production rate and inhibiting cancer cells growth in fenofibrate-treated cells." (PMID 26869356, 2016). "Seven up-regulated genes including CYC1, MIF, LAMB3, TUBB2, UBE2C and TRAP1 had been previously proposed as candidate common cancer biomarkers based on a previous extensive comparison among various cancers and normal tissues which did not, however, include NPC or NP." (PMID 18570662, 2008). "The genes which have been reported to involve the cancer cell invasion (ENPP2, ADCY8), dysregulated cellular metabolism (CYC1), and angiogenesis (ANGPT1), immune inhibition (ANXA3) amplified notably in the high-risk group, which might elaborate the aggressiveness and malignancy in this group." (PMID 34568069, 2021). "For example, human cytochrome c1, whose gene is regulated by E2F, participates in an electron transport chain and the mitochondria pathway of apoptosis whereas a similar set of electron transport-related genes (COX8, CYB5-M, CYP51A1, FDXR and SUCLG1) were found to be E2F4-bound in cancer cell lines." (PMID 22076139, 2011).
cancer (continued). "Among the 16 common cancer biomarkers identified as highly predictive by the previous study which did not include NPC samples, 6 genes (CYC1, MIF, LAMB3, TSTA3, TUBB2, and UBE2C) were found to be highly expressed in NPC by the study." (PMID 18570662, 2008).
tumor (12 papers, 2009 to 2025). "Digging into the mechanism of decreased tumor metastasis caused by silencing CYC1, we find reduced activity of mitochondrial complex III, increased ratio of AMP to ATP, and increased phosphorylation of AMPK." (PMID 27239088, 2016). "This study not only shows prognostic value of CYC1, but also helps us to further understand the role of CYC1 played in tumor metastasis." (PMID 27239088, 2016). "We concluded that CYC1 promoted tumor metastasis via suppressing activation of AMPK and contributed to tumor growth via facilitating production of ATP." (PMID 27239088, 2016). "At the initial stage of tumorigenesis, these mutated genes might be tumor-initiating SNVs in conjunction with the CNAs of FAT1, MYC, PARP10, and CYC1." (PMID 30143682, 2018). "Furthermore, significant decrease of CYC-1 protein was observed in serum samples of 3 of 4 patients after surgical removal of the tumor." (PMID 19445706, 2009). "In addition, expression levels of CYC1 were higher in tumor tissues with lymph node metastasis." (PMID 27239088, 2016). "More specifically, high mRNA expression levels of CYC1 (Cytochrome C1) and UQBP (Ubiquinol-Cytochrome C Reductase Binding Protein), key components of complex III, are both associated with significantly reduced progression-free survival (i.e., higher tumor recurrence)." (PMID 27136895, 2016). "In LGG, pathways associated with a good prognosis include oxidative phosphorylation (LHPP, PPA1, CYC1), supported by a high WWOX/HIF1A ratio, which improves energy metabolism and reduces tumour aggressiveness." (PMID 41007296, 2025). "The FC in gene expression of each marker in tumour samples relative to healthy controls was determined using the 2− ΔΔCt method normalised to the average of 7 housekeeping genes (YWHAZ, CYC1, SDHA, TBP, GAPDH, UBC and 18s RNA)." (PMID 41034696, 2025).
infection (4 papers, 2011 to 2025). The state of being infected such as from the introduction of a foreign agent such as serum, vaccine, antigenic substance or organism. "Some proapoptotic molecules, including cyc1 (cyto c), caspase-2 (Casp2), Txnip and Casp7, Cebpb, Eaf2, were significantly down-/upregulated after infection with Brucella, and this could result in apoptosis of infected cells." (PMID 22216095, 2011).
CYC1 also shares sentences with these, for which no sentence is quoted: multiple system atrophy (2 papers); neurodegenerative disease (2); Parkinson disease (2); progressive supranuclear palsy (2); amyotrophic lateral sclerosis (1); benign breast tumor (1); bipolar disorder (1); bladder cancers (1); breast (1); breast intraductal carcinoma (1); cardiomyopathies (1); colon tumor (1); escherichia coli infection (1); frontotemporal dementia (1); Hypertension (1); lung carcinoma (1); major depressive disorder (1); metastatic tumors (1); mitochondrial disease (1); nasopharyngeal carcinoma (1); ovarian tumor (1); polycystic ovary syndrome (1); Salmonella Infections (1); sarcopenia (1); schizophrenia (1); spinal muscular atrophy (1); thyroid cancer (1); type 2 diabetes (1); uveal melanoma (1).